ZNF75D (zinc finger protein 75D)
Description:
May be involved in transcriptional regulation.
Synonyms: ZNF75; ZNF82; ZKSCAN24; D8C6; ZSCAN28
Tractability: No criterion of Open Targets' tractability assessment is met for any kind of drug.
Gene: Protein-coding gene on chromosome X (135,248,590 to 135,344,113, reverse strand). Ensembl gene ENSG00000186376.
Subcellular location: Nucleus
Subcellular location (Human Protein Atlas): Golgi apparatus; Nucleoplasm
Pathways (Reactome):
Gene expression (Transcription): Generic Transcription Pathway
Gene Ontology:
Molecular function: DNA-binding transcription factor activity, RNA polymerase II-specific; RNA polymerase II cis-regulatory region sequence-specific DNA binding; zinc ion binding
Biological process: regulation of transcription by RNA polymerase II; regulation of DNA-templated transcription
Cellular component: nucleus
Homologues: Orthologues: chimpanzee ZNF75D (99% identical), macaque ZNF75D (95% identical), pig ZNF75D (77% identical), dog ZNF75D (77% identical). Paralogues in human: ZNF75A (67% identical), ZKSCAN3 (28% identical), ZKSCAN4 (28% identical), ZNF397 (28% identical), ZSCAN22 (27% identical), ZKSCAN1 (27% identical), ZNF394 (27% identical), ZNF263 (27% identical), ZKSCAN8 (27% identical), ZSCAN30 (27% identical), ZSCAN12 (26% identical), ZSCAN21 (26% identical), and 18 more.
Diseases named in the same sentence as ZNF75D in open-access papers:
ZNF75D is named in the same sentence as 2 diseases in open-access papers, as found by Europe PMC text mining. Sharing a sentence is not in itself a finding about the gene and the disease. The quoted sentences say what the papers report.
breast carcinoma (1 paper, 2022). "It suggests that upregulated DPP9, LRRC20 and TTBK2 together with downregulated TTC17, ZNF75D and CYTH2 may play pivotal role in the orchestrated adaptive homing of metastatic breast cancer cells in bone niche." (PMID 35685372, 2022).
ZNF75D also shares sentences with these, for which no sentence is quoted: tumor (1 paper).